EEF1G (eukaryotic translation elongation factor 1 gamma)
Description:
Probably plays a role in anchoring the complex to other cellular components.
Synonyms: EF1G; GIG35
Tractability: PROTAC: UniProt records ubiquitination sites on it; ubiquitination databases record sites on it; its protein half-life has been measured.
Gene: Protein-coding gene on chromosome 11 (62,559,595 to 62,574,086, reverse strand). Ensembl gene ENSG00000254772.
Subcellular location (Human Protein Atlas): Cytosol; Golgi apparatus
Pathways (Reactome):
Disease: Signaling by ALK fusions and activated point mutants
Metabolism of proteins: Eukaryotic Translation Elongation
Gene Ontology:
Molecular function: cadherin binding; protein binding; translation elongation factor activity
Biological process: response to virus; translational elongation
Cellular component: cytoplasm; endoplasmic reticulum; extracellular exosome; membrane; nucleus; cytosol; eukaryotic translation elongation factor 1 complex
Genetic constraint (gnomAD): Loss-of-function variants: 14 observed, 55.15 expected, observed/expected ratio (o/e) 0.25, 90% interval 0.17 to 0.4. The upper end of that interval is the gene's LOEUF score, 0.4, which puts it in group 1 of 6, group 1 being the genes least tolerant of losing a copy. Missense variants: 322 observed, 534.47 expected, observed/expected ratio (o/e) 0.6, 90% interval 0.55 to 0.66. Synonymous variants: 180 observed, 200.97 expected, observed/expected ratio (o/e) 0.9, 90% interval 0.79 to 1.01.
Homologues: Orthologues: chimpanzee EEF1G (100% identical), macaque EEF1G (99% identical), mouse Eef1g (98% identical), guinea pig EEF1G (97% identical), rabbit EEF1G (94% identical), tropical clawed frog eef1g (78% identical), zebrafish eef1g (78% identical), Drosophila melanogaster eEF1gamma (59% identical), Caenorhabditis elegans eef-1G (46% identical). Paralogues in human: GSTT2B (15% identical), GSTT2 (15% identical), GDAP1L1 (13% identical), GDAP1 (13% identical), CLIC4 (12% identical), CLIC6 (12% identical), GSTT4 (12% identical), CLIC1 (12% identical), CLIC5 (11% identical), CLIC2 (11% identical), CLIC3 (11% identical), GSTO1 (8% identical), and 2 more.
Diseases named in the same sentence as EEF1G in open-access papers:
EEF1G is named in the same sentence as 41 diseases in open-access papers, as found by Europe PMC text mining. Sharing a sentence is not in itself a finding about the gene and the disease. The quoted sentences say what the papers report.
breast carcinoma (3 papers, 2018 to 2025). "Likewise, increased EEF1G transcript levels showed positive correlation with DMFS and RFS in breast cancer." (PMID 29342219, 2018).
lung carcinoma (3 papers, 2018 to 2022). "Among the dysregulated genes in three independent cohort studies in the Oncomine database, EEF1G was detected as the poor prognosis protein in lung cancer." (PMID 36139528, 2022). "Additionally, overexpression of EEF1G has been reported previously in lung cancer, and it showed a correlation with poor prognosis in patients." (PMID 36139528, 2022). "Overexpression of many factors predicted poor prognosis in breast (EEF1D, EEF1E1, EEF2) and lung cancer (EEF1A2, EEF1B2, EEF1G, EEF1E1)." (PMID 29342219, 2018). "Overexpression of most factors predicted a poor prognosis in breast (EEF1D, EEF1E1, and EEF2) and lung cancer (EEF1A2, EEF1B2, EEF1G, EEF1E1) in KM analysis." (PMID 29342219, 2018). "Likewise, increased transcript levels of EEF1G and EEF1E1 led to poor OS and FP in lung cancer." (PMID 29342219, 2018).
ovarian carcinoma (3 papers, 2018 to 2024). A malignant neoplasm originating from the surface ovarian epithelium. "Regarding EEF1E1, studies have found that EEF1E1 is overexpressed in most tumors, including ovarian cancer, and that high expression of EEF1G predicts better OS and PFS rates in OC patients, which is consistent with our research results." (PMID 34825509, 2021). "In this study, we confidently identified the marker combination of EEF1G + MSLN + BCAM + TAGLN2 which showed upregulation in both serum and tissue an outperforming marker panel against currently available markers for ovarian cancer." (PMID 38918474, 2024). "Higher expression of EEF1G predicted better OS and PFS in ovarian cancer patients." (PMID 29342219, 2018).
colon adenocarcinoma (2 papers, 2018 to 2022). "An overexpression of EEF1G has been reported in gastric carcinoma, colon adenocarcinoma, and pancreatic cancer." (PMID 36038612, 2022). "Eukaryotic translation elongation factor 1 gamma (EEF1G) has been reported to be overexpressed in gastric carcinoma, colon adenocarcinoma, and pancreatic cancer." (PMID 29342219, 2018).
colorectal cancer (2 papers, 2004 to 2018). A primary or metastatic malignant neoplasm that affects the colon or rectum. "SurvExpress analysis revealed significantly reduced mRNA levels of EEF1A1, EEF1B2, EEF1E1, EEF1G and EEF2 in the high-risk group, in colorectal cancer and, predicted poor survival." (PMID 29342219, 2018). "Oncomine analysis of colorectal cancer with the pre-specified thresholds didn’t return any datasets with significant difference in mRNA levels, for EEF1A1, EEF1A2, EEF1B2, EEF1G and EEF2." (PMID 29342219, 2018).
adenoma (1 paper, 2004). A neoplasm arising from the epithelium. "RACK1, ACBP, CDH17 and EEF1G were significantly overexpressed in low-grade adenomas, whereas DEFA5 was significantly overexpressed in high-grade adenomas and suppressed in adenocarcinomas." (PMID 14710232, 2004).
Burkitt lymphoma (1 paper, 2018). A rare form of malignant mature B-cell non-Hodgkin lymphoma. "Likewise for EEF1G, significant overexpression of the gene was observed in Brune’s dataset for Burkitt's lymphoma and diffuse large B-Cell Lymphoma." (PMID 29342219, 2018).
diabetes (1 paper, 2025). "Ribosomal and translational machinery components, such as RPS26, RPS26L1, and EEF1G, highlight potential shifts in protein synthesis capacity or cellular homeostasis that accompany preclinical diabetes." (PMID 40740938, 2025).
ductal breast carcinoma in situ (1 paper, 2018). A carcinoma entirely confined to the mammary ducts. "Likewise for EEF1G expression, all the four datasets showed a significant downregulation in the tumor subtypes, including invasive ductal breast carcinoma and ductal breast carcinoma in situ." (PMID 29342219, 2018).
glioblastoma (1 paper, 2018). The most malignant astrocytic tumor (WHO grade IV). "Glioblastoma and glioma dataset revealed that EEF1A1, EEF1G, EEF1D and EEF2 were significantly overexpressed in tumor tissues whereas EEF1A2 was significantly downregulated." (PMID 29342219, 2018).
influenza (1 paper, 2023). An acute viral infection of the respiratory tract, occurring in isolated cases, in epidemics, or in pandemics; it is caused by serologically different strains of viruses (influenzaviruses) designated A, B, and C, has a 3-day incubation period, and usually lasts for 3 to 10 days. "RPL3 and EEF1G, which enable different ribosomal-related enzyme functions, are commonly downregulated during initial acute influenza infection." (PMID 37533854, 2023). "In a separate pediatric study, EEF1G mRNA expression and specifically RPL31, were reported to be decreased in PBMCs from influenza-infected children following hospitalization and could be used to distinguish between influenza and bacterial infections (with and without lung involvement)." (PMID 37533854, 2023).
Kidney clear cell carcinoma (1 paper, 2018). "SurvExpress analysis using TCGA-KIRC (Kidney clear cell carcinoma) dataset showed that higher expression levels of EEF1A1, EEF1G and EEF2 predicted better survival in low-risk group patients." (PMID 29342219, 2018). "As per TCGA analysis, expression levels of EEF1A1, EEF1B2, EEF1G, EEF1D and EEF2 were significantly upregulated in kidney clear cell carcinoma while that of EEF1E1 was downregulated." (PMID 29342219, 2018).
neuroblastoma (1 paper, 2025). Neuroblastoma (NB) is the most common solid, extracranial childhood tumor. "Seven of our hits (Tubb1, Tubb5, Eef1a1, Eef1g, Gapdh, Nudc, Actg1) are present in their list of 52 enriched proteins from TGM2 stimulated N2a neuroblastoma cells." (PMID 41142754, 2025).
Obesity (1 paper, 2021). Accumulation of substantial excess body fat. "Furthermore, the results illustrate that the mRNA expression levels of PCM1, SIRT1, EEF1G, PTEN and RPS2 were significantly decreased in the obesity compared with the control group." (PMID 34248836, 2021).
varicocele (1 paper, 2020). A condition characterized by the dilated tortuous veins of the spermatic cord with a marked left-sided predominance. "Other proteins associated with normal sperm functions, such as SEMG1 and SEMG2, acrosin (ACR), elongation factor 1-gamma (EEF1G) and PGK2 were downregulated in SP from varicocele, probably explaining the poor sperm motility and concentration usually found in these patients." (PMID 32987677, 2020).
vitiligo (1 paper, 2024). Generalized well circumscribed patches of leukoderma that are generally distributed over symmetric body locations and is due to autoimmune destruction of melanocytes. "The role of EEF2, EEF1G and PSMA2 in vitiligo or inflammation pathways remains unclear." (PMID 38715599, 2024).
cancer (10 papers, 2012 to 2025). A tumor composed of atypical neoplastic, often pleomorphic cells that invade other tissues. "Abnormal EEF1G expression has been implicated in oncogenic activities across diverse cancer types, suggesting its potential as both a diagnostic and prognostic marker." (PMID 40926349, 2025). "We failed to obtain any eEF1G knockout cells most likely because eEF1G is an essential gene for proliferation and survival in human cancer cell lines." (PMID 30008712, 2018). "Overall, we see that in addition to EEF1A2; EEF1G, EEF1D, EEF1E1 and EEF2 are significantly upregulated in different cancer types and are associated with better and worse survival outcome in specific cancers." (PMID 29342219, 2018). "EEF1G has been reported to be overexpressed in multiple cancers, including CRC, but little is known about its potential roles in cancer progression." (PMID 38542474, 2024). "We also found that the previously reported pro-tumorigenic roles of EEF1G and EEF1D can be extended to other cancers viz." (PMID 29342219, 2018). "Higher expression of EEF1A2, EEF1B2, EEF1G, EEF1D, EEF1E1 and EEF2 was observed in most of the cancer types, whereas reverse trend was observed for EEF1A1." (PMID 29342219, 2018). "Additionally, another study showed how the co‐upregulation of EEF1G and TRAP1 contributed to the synthesis of stress‐responsive proteins, an important adaptive mechanism enabling cancer cells to counteract antitumor therapies." (PMID 40926349, 2025). "Keeping these lacunae in hindsight, we have undertaken a pan-cancer approach for comprehensive analysis of expression levels of seven elongation factors namely, EEF1A1, EEF1A2, EEF1B2, EEF1G, EEF1D, EEF1E1 and EEF2, using publicly available databases (Oncomine and TCGA)." (PMID 29342219, 2018). "In addition to EEF1A2, other translation factors EEF1B2, EEF1G, EEF1D, EEF1E1, and EEF2 were also found to be frequently overexpressed in different cancers." (PMID 29342219, 2018).
tumor (9 papers, 2015 to 2025). "Notably, a study showed the role of oncogene‐induced ubiquitination of EEF1G in tumor suppression, highlighting its function in mitigating uncontrolled cellular proliferation due to aberrant oncogenic signaling." (PMID 40926349, 2025). "Yet, the consistence in EEF1G expression independent of tumor size suggests minimal impact on the observed EEF1G‐prognosis association." (PMID 40926349, 2025). "EEF1G, beyond its conventional role in protein translation, plays a key role in the cellular stress response and is particularly responsive to changes in the tumor microenvironment." (PMID 40926349, 2025). "Interestingly, we noticed that eEF1a, belonging to the same family as eEF1g, has been studied for its impact on tumor cell proliferation by regulating the G1-to-S phase transition." (PMID 40435287, 2025). "Additionally, the identification of key genes interacting with EEF1G across different BMI statuses further emphasizes the nuanced relationship between EEF1G expression, the tumor microenvironment, and metabolic factors in BC." (PMID 40926349, 2025). "In the present study we identified four candidate tumor-associated antigens, including chaperonin containing TCP1 subunit 5 (CCT5), heat shock 70 kDa protein 8 isoform 1 (HSP70), eukaryotic translation elongation factor 1 gamma (eEF1), and phosphoglycerate mutase 1 (PGM1)." (PMID 28969060, 2017). "The TN clusters (TN and TN+Her2) include proliferative proteins (MCM3 and 5), translation related proteins (RCL1, MRPS27, EIF2S2 and EEF1G) and metabolic enzymes (glutaminase and hexokinase 2), which reflect the higher dependence on glutamine and glucose of TN versus the other tumours." (PMID 26725330, 2016). "EEF1B2, EEF1G, EEF1D, EEF1E1 and EEF2, presented increased transcript levels in tumor group compared to normal, the most prominent being EEF1E1." (PMID 29342219, 2018). "TCGA analysis further confirmed that mRNA levels of EEF1A1, EEF1A2, EEF1B2, EEF1G and EEF2 were significantly downregulated in tumor tissues than normal." (PMID 29342219, 2018). "However, significant overexpression of EEF1A2, EEF1G, EEF1D, EEF1E1 and EEF2 was seen in tumor tissues." (PMID 29342219, 2018). "However TCGA analysis revealed that in addition to EEF1E1, mRNA levels of EEF1A2, EEF1G, and EEF1D are also significantly upregulated in tumor tissues." (PMID 29342219, 2018).
adenocarcinoma (3 papers, 2004 to 2022). A common cancer characterized by the presence of malignant glandular cells. "Likewise, elevated mRNA levels of EEF1B2, EEF1G and EEF2 were significantly correlated with worse survival outcome in adenocarcinoma." (PMID 29342219, 2018).
infection (3 papers, 2016 to 2025). The state of being infected such as from the introduction of a foreign agent such as serum, vaccine, antigenic substance or organism. "RT-qPCR analysis (using β-actin for normalization) confirmed that eEF1G mRNA levels remain stable throughout infection." (PMID 41157639, 2025). "To elucidate the mechanism by which eEF1G inhibits PDCoV replication, we first assessed whether its expression or localization is altered upon infection." (PMID 41157639, 2025).
EEF1G also shares sentences with these, for which no sentence is quoted: esophageal cancer (4 papers); gastric carcinoma (2); gastric tumors (2); lymph node metastases (2); pancreatic cancer (2); acute myelogenous leukaemia (1); bacterial infections (1); bone osteosarcoma (1); cardiac hypertrophy (1); Cardiovascular disease (1); cervical cancer (1); chronic periodontitis (1); diffuse large B-cell lymphoma (1); gastrointestinal carcinoma (1); glioma (1); hepatocellular carcinoma (1); invasive ductal breast carcinoma (1); leukemia (1); polymyositis (1); prostate carcinoma (1); viral infection (1).